CD74 (CD74 molecule)
Diseases named in the same sentence as CD74 in open-access papers (continued):
Sharing a sentence is not in itself a finding about the gene and the disease.
Lipedema (2 papers, 2023 to 2025). Disorder of adipose tissue characterized by symmetric and bilateral enlargement of the lower extremities due to abnormal deposition of subcutaneous fat often in obese women. "In conclusion, we showed that MIF-1 mRNA, CD74 mRNA and their cellular levels are increased in the subcutaneous adipose tissue of lipedema patients, whereas MIF-2 expression remains unchanged." (PMID 37887430, 2023). "A histopathological analysis was performed to further investigate the increased MIF-1 and CD74 levels of the lipedema tissue samples." (PMID 37887430, 2023). "We were able to highlight a statistically significant overexpression of MIF-1 and its receptor CD74 on an mRNA level in the subcutaneous adipose tissue of lipedema patients." (PMID 37887430, 2023). "In this study, the expression of MIF-1, MIF-2 and CD74—a common receptor for both cytokines—was analyzed in tissue samples of 11 lipedema and 11 BMI-matched, age-matched and anatomically matched control patients using qPCR and immunohistochemistry (IHC)." (PMID 37887430, 2023). "The mRNA expression of MIF-1 (mean 1.256; SD 0.303; p = 0.0485) and CD74 (mean 1.514; SD 0.397; p = 0.0097) were significantly elevated in lipedema patients, while MIF-2 expression was unaffected (mean 1.004; SD 0.358; p = 0.9718)." (PMID 37887430, 2023). "A separate comparison of stage II and III lipedema with the control group resulted in a significant overexpression of CD74 in stage II lipedema (mean 1.703; SD 0.3959; p = 0.0071) and a significant overexpression of MIF-1 in stage III lipedema (mean 1.370; SD 0.3266; p = 0.0383)." (PMID 37887430, 2023). "However, the histological analysis of CD74 did confirm the results of overexpression in lipedema patients (mean (L) 7.727 ± 1.849 and (C) 5.181 ± 1.601; p = 0.0026)." (PMID 37887430, 2023). "The precise function of MIF-1 and CD74 in lipedema remains unclear." (PMID 37887430, 2023). "How MIF-1 and CD74 promote the adipose tissue hypertrophy in lipedema is also unknown." (PMID 37887430, 2023). "In another study, mRNA expressions of MIF-1 and CD74 were significantly increased in patients with lipedema, while MIF-2 expression was unaffected, suggesting a possible contribution of the MIF family via the MIF-1-CD74 axis in lipedema." (PMID 40419722, 2025). "Compared with the housekeeping genes and control group, the lipedema patients showed a statistically significant overexpression of MIF-1 (mean 1.256; SD 0.303; p = 0.0485) and CD74 (mean 1.514; SD 0.397; p = 0.0097)." (PMID 37887430, 2023). "In this study, we evaluated the expression of MIF-1, MIF-2 and their receptors CD74, CXCR2 and CXCR4, which were investigated in lipedema patient samples, suggesting their possible involvement in the development of this still not fully understood and underdiagnosed disease." (PMID 37887430, 2023). "However, it was shown that CD74, which builds a complex with CD44, fosters cell survival and inflammation, which may apply to adipose tissue in lipedema patients." (PMID 37887430, 2023). "However, we do not believe that MIF-1 or CD74 will fill this role when it comes to lipedema because it is ubiquitously expressed in the presence of inflammation and because the specific inflammatory process seems to be localized in the adipose tissue of the affected limbs." (PMID 37887430, 2023).
liver cirrhosis (2 papers, 2013 to 2024). "Surprisingly, expression of Cd74 is closely related to inhibition of fibrogenesis, which can protect against liver cirrhosis." (PMID 23823021, 2013).
liver disease (2 papers, 2013 to 2022). "Cd74 expression was recently examined in various cell types other than antigen-presenting cells, including liver cells, and is particularly important in complex immunological functions and in the link between chronic inflammation and liver disease." (PMID 23823021, 2013).
lymphopenia (2 papers, 2022 to 2023). Reduction in the number of lymphocytes. "The most likely explanation for this difference to the frequencies of CD74+ cells was that most patients present with lymphopenia during the acute phase of SARS-CoV-2 infection." (PMID 37946732, 2023). "For examples, monocyte alterations (CD74, CIITA mRNA), lymphopenia (CD3, IL7R mRNA), increased anti-inflammatory response (IL10, IL1RN mRNA), altered IFN response (OAS2, IFNG mRNA) were observed." (PMID 36389738, 2022).
mammary adenocarcinoma (2 papers, 2013 to 2015). "Although specific data for HER2/neu and EGFR expression by mammary adenocarcinoma (SKBr-3) is limited, other neoplastic cell types like metastatic multiple myeloma are known to internalize approximately 8×106 molecules of anti-CD74 monoclonal antibody per day." (PMID 26225219, 2013).
medulloblastoma (2 papers, 2021 to 2026). A malignant, invasive embryonal neoplasm arising from the cerebellum. "Based on these prior studies and the inverse correlation of MIF and CD74 in our tumor model, we propose that MIF functions in medulloblastoma to bias myeloid cells toward an Igf1+ phenotype, and acts more effectively in G-Smo tumors, which have higher Mif expression." (PMID 34021242, 2021).
meningioma (2 papers, 2023). A generally slow growing tumor attached to the dura mater. "In contrast, there was a modest but significant increase in relative expression of myeloid markers (CD14, CD33 and CD74) in NF2 meningiomas, suggesting higher infiltration of NF2 tumors by myeloid cells." (PMID 36937440, 2023). "Immunofluorescence staining results revealed the presence of MIF (green fluorescence) and CD74 (red fluorescence) in atypical, transitional, fibrous, clear cell, and endothelial subtypes of meningiomas." (PMID 37880655, 2023). "In order to ensure the robustness of the broad expression of MIF and CD74 observed within meningiomas, a subsequent investigation was conducted involving an additional cohort of ten meningioma cases." (PMID 37880655, 2023). "We have identified a common mechanism in different pathological subtypes (including atypical, transitional, fibrous, and clear cell) of meningiomas, namely the ubiquitous presence of MIF and CD74-positive macrophage interactions." (PMID 37880655, 2023). "In order to investigate the extensive MIF-CD74 interactions in meningiomas, immunofluorescence staining was performed on five distinct types of meningiomas, including DAPI, MIF, CD74, and the meningioma marker Vimentin." (PMID 37880655, 2023). "We propose that blocking CD74-positive macrophages from receiving MIF signals and inhibiting their progression to a pro-tumorigenic state may be a key therapeutic strategy for treating different types of meningiomas." (PMID 37880655, 2023).
myositis (2 papers, 2022 to 2024). "In terms of myositis, marker genes encoding lysosomal proteins including cathepsins (CTSA, CTSK), IFI30 Lysosomal Thiol Reductase (IFI30) and CD74 Molecule (CD74) suggested active lysosome and immune cells activities in muscle turnover." (PMID 38342952, 2024).
Neonatal sepsis (2 papers, 2022 to 2024). Systemic inflammatory response to infection in newborn babies. "IP-10 production in infants reflects a consequent Th1 response and as such, it may represent in conjunction with a reduced CD74 expression, despite IFNγ stimulation, a signature for severely dysregulated response associated with neonatal sepsis." (PMID 36509812, 2022). "In this study, we evaluated the diagnostic and prognostic accuracy of transcriptional (CX3CR1, CD74) and proteic (IL6, IL10, IP-10, PCT) biomarkers and their association with clinics and maternal risk factors for neonatal sepsis." (PMID 36509812, 2022). "Following neonatal sepsis, at week 4, CD74 was significantly lower in septic than in healthy newborns." (PMID 36509812, 2022). "Our study further extend CD74 prognosis utility in neonatal sepsis." (PMID 36509812, 2022). "Kinetics of CD74 expression following neonatal sepsis showed a prolonged impairment in survivors." (PMID 36509812, 2022). "Accuracy of transcriptional (CD74, CX3CR1), proteic (PCT, IL-6, IL-10, IP-10) biomarkers and clinical characteristics to diagnose and prognose neonatal sepsis were measured." (PMID 36509812, 2022). "There are no data on value of CD74 and CX3CR1 for the prognosis or diagnosis of neonatal sepsis, which hamper current use of these biomarkers in neonates and children." (PMID 36509812, 2022).
osteoarthritis (2 papers, 2022 to 2025). A noninflammatory degenerative joint disease occurring chiefly in older persons, characterized by degeneration of the articular cartilage, hypertrophy of bone at the margins and changes in the synovial membrane. "HLA-DRB1, CD74 and APOL4 were also found previously to be induced by IFN-γ in osteoarthritis chondrocytes." (PMID 35326396, 2022).
parasite infection (2 papers, 2021 to 2022). "Thus, POR is indirectly responsible for regulation of expression of CIITA along with the molecules of MHC II group such as CD74, HLADQA1, HLADMA, HLADQB1 and HLADRB5 previously identified as genes responsible for inhibition of parasite infection." (PMID 34946170, 2021).
pneumonia (2 papers, 2020 to 2024). An acute, acute and chronic, or chronic inflammation focally or diffusely affecting the lung parenchyma, caused by an infection in one or both of the lungs (by bacteria, viruses, fungi, or mycoplasma.). "Salahaldin A. Tahir and colleagues additionally discovered a significant 1.34-fold increase in autoantibodies against CD74 in patients with immune-related pneumonia after receiving immune checkpoint inhibitor therapy, suggesting a role for CD74 autoantibodies in pneumonia." (PMID 38983925, 2024). "However, according to a study in children with severe viral pneumonia, CD74+ cells predominate in histopathological types with interstitial pneumonia as the pathological type, but no changes in CD74 have been observed in adults who developed pneumonia without immunotherapy." (PMID 33317597, 2020).
primary biliary cholangitis (2 papers, 2024 to 2025). Primary biliary cholangitis (PBC) is a chronic and slowly progressive cholestatic liver disease of autoimmune etiology characterized by injury of the intrahepatic bile ducts that may eventually lead to liver failure. "Supporting their clinical relevance, elevated serum levels of soluble CD74 have been reported in patients with autoimmune hepatitis (AIH) and primary biliary cholangitis (PBC)." (PMID 40565363, 2025).
seminoma (2 papers, 2023 to 2024). A radiosensitive malignant germ cell tumor found in the testis (especially undescended), and extragonadal sites (anterior mediastinum and pineal gland). "To further validate, we conducted immunostaining and detected MIF and CD74 signals at the protein level in the seminoma tissues." (PMID 38123589, 2023). "CD74 levels and clinical features were then investigated, finding negative associations between CD74 and high-grade UCEC and BLCA and higher CD74 expression in patients with HPV + HNSC, IDHwt-LGG, EBV-STAD, and seminoma-TGCT in comparison with other subtypes." (PMID 38582956, 2024).
small cell lung carcinoma (2 papers, 2020 to 2025). Small cell lung cancer (SCLC) is a highly aggressive malignant neoplasm, accounting for 10-15% of lung cancer cases, characterized byrapid growth, and early metastasis. "Upregulation of nuclear YAP1 is associated with poor survival, and YAP1 enhances the resistance to drugs through CD74 signaling in small cell lung cancer." (PMID 41184230, 2025). "In addition, inhibition of CD74 by ISO‐1 can increase drug sensitivity of small cell lung cancer cells significantly." (PMID 31692299, 2020).
steatosis (2 papers, 2025). Increased lipid within the cytoplasm of cells. "Given that diclofenac also induces steatosis, its interaction with its receptor, CD74, is critical." (PMID 40565363, 2025). "Previous data indicated that MIF has a hepatoprotective effect in steatosis and fibrosis by promoting the CD74/AMPK pathway in hepatocytes and Mif–/– mice on a non-Western-type HFD showed enhanced lipid accumulation in the liver, which was associated with upregulated Srebp-1 and Fasn levels." (PMID 40055309, 2025).
T-cell leukemia (2 papers, 2007 to 2014). A malignant disease of the T-lymphocytes in the bone marrow, thymus, and/or blood. "To study the effects of CD74 on Fas-mediated apoptosis, we first tested CD74 expression in 4 B-lymphoma cell lines (BJAB, Ramos, Raji, and Daudi) and in the Jurkat (T-cell leukemia) cell line by WB." (PMID 25304249, 2014).
thymoma (2 papers, 2020 to 2022). A neoplasm arising from the epithelial cells of the thymus. "The positive correlation between the CD74 and HLA-DRA expression in our study was also found in another report on invasive thymomas." (PMID 35208514, 2022).
tuberculosis (2 papers, 2024 to 2025). A chronic, recurrent infection caused by the bacterium Mycobacterium tuberculosis. "KEGG pathway analysis revealed that the enrichment pathways of the genes coexpressed with CD74 were involved in the hematopoietic cell lineage, cell adhesion molecules (CAMs), natural killer cell-mediated cytotoxicity, tuberculosis, the NF-kappa B signaling pathway and Epstein–Barr virus infection." (PMID 39118044, 2024). "We also employed an LV driving the expression of CD74 fused with SIINFEKL and with an immunodominant MHC-II-restricted peptide found in mycobacterium tuberculosis (TB) hereon indicated as SIINFEKL.TB." (PMID 40216735, 2025).
abdominal aortic aneurysm (1 paper, 2024). Enlargement and ballooning of the vessel that supplies arterial blood to the abdomen, pelvis and legs. "Our research indicate that MSC-Exo protect against abdominal aortic aneurysm formation through CD74 modulation of macrophage polarization in mice." (PMID 39098899, 2024).
acinar adenocarcinoma (1 paper, 2023). "In 2020, CD74-NRG2α was identified in a female acinar adenocarcinoma patient from Japan." (PMID 37958963, 2023).
acute leukemia (1 paper, 2025). A clonal (malignant) hematopoietic disorder with an acute onset, affecting the bone marrow and the peripheral blood. "The results of our study suggest that the increased expression of ACTB and the molecular interplays involving “HBA1&HBB," “HBB&HBA1," “IGKV1-5&IGHV4-31," “IGHV4-31&IGKV1-5," “HLA-DRA&CD74" and “ACTB&ACTB" might contribute to the progression of acute leukemia." (PMID 40338916, 2025). "Furthermore, the suppression of ACTB and the molecular interactions involving pairs such as “HBA1&HBB", ”HBB&HBA1", “IGKV1-5&IGHV4-31", “IGHV4-31&IGKV1-5", “HLA-DRA&CD74", and “A CTB&ACTB" might provide essential insights into unraveling the intricate mechanisms of acute leukemia." (PMID 40338916, 2025).
acute lung injury (1 paper, 2016). A condition of lung damage that is characterized by bilateral pulmonary infiltrates (pulmonary edema) rich in neutrophils, and in the absence of clinical heart failure. "CD74 is expressed on the cell surface of pulmonary macrophages and contributes to macrophage migration inhibitory factor (MIF)-induced inflammatory response in acute lung injury (ALI)." (PMID 27444250, 2016).
acute T-cell lymphoblastic leukemia (1 paper, 2024). "The role of CD74 and COPA in regulating the immunosuppressive microenvironment as well as the function of LGALS9 and HAVCR2 in regulating T-cell responses signified that they may be potential targets for the treatment of acute T-cell lymphoblastic leukemia." (PMID 39422621, 2024).
age-related hearing loss (1 paper, 2026). "Targeting macrophage CD74 may offer therapeutic potential for preventing and treating age-related hearing loss." (PMID 41884819, 2026).
alcohol abuse (1 paper, 2024). The use of alcoholic beverages to excess, either on individual occasions ("binge drinking") or as a regular practice. "The data suggested that risk factors including alcohol abuse and hepatitis virus infection can affect the prognostic value of CD74 in HCC patients." (PMID 39118044, 2024). "In summary, CD74 was highly expressed in HCC samples and was significantly associated with alcohol abuse and hepatitis virus, which determine the prognosis of patients with HCC." (PMID 39118044, 2024).
allergic asthma (1 paper, 2025). A asthma with a basis in a pathological type I hypersensitivity reaction. "We have previously shown that CD74 is required for MIF‐licensed MSC immunomodulation and to significantly increase the retention of human BM‐MSCs in vivo in an HDM model of allergic asthma." (PMID 39502000, 2025).
Arrhythmia (1 paper, 2022). Any cardiac rhythm other than the normal sinus rhythm. "This information suggests that MIF/CD74 signaling is a potential therapeutic intervention for arrhythmia." (PMID 36712241, 2022).
arrhythmogenic right ventricular cardiomyopathy (1 paper, 2022). "In additional, bioinformatic analysis of the myocardium of patients with arrhythmogenic right ventricular cardiomyopathy (ARVC) versus normal controls revealed an immune-related hub module, which Protein-Protein Interaction Network analysis identified CD74 as one of the most important hub genes." (PMID 36712241, 2022).
B-cell acute lymphoblastic leukemia (1 paper, 2023). A neoplasm of lymphoblasts committed to the B-cell lineage, typically composed of small to medium-sized blast cells. "RNA seq first identified a CD74-PDGFRB fusion in a 2.4-year-old male with B-cell acute lymphoblastic leukemia." (PMID 37958963, 2023).
brain inflammation (1 paper, 2021). "Our present data reveal that the activation of the Mif/Cd74 signaling axis may be involved in HAM-induced brain inflammation." (PMID 34881090, 2021). "Thus, we believe that aging increases neuronal secretion of Mif which binds to Cd74 and activates HAM to evoke brain inflammation." (PMID 34881090, 2021). "Together, these previous reports support our findings that Cd74 may function as a signal transducer in HAM, in charge of receiving stimuli to evoke brain inflammation." (PMID 34881090, 2021).
carotid atherosclerosis (1 paper, 2022). A thickening and loss of elasticity of the walls of carotid arteries that occur with formation of atherosclerotic plaques. "The aim of this study was to determine whether CD74 expression is associated with clinical symptoms or plaque severity among patients with carotid atherosclerosis." (PMID 35050177, 2022). "The aim of this study was to investigate whether CD74 levels in atherosclerotic lesions are associated with inflammation, apoptosis, plaque severity, and clinical symptoms among patients with carotid atherosclerosis." (PMID 35050177, 2022). "Next, we investigated whether CD74 expression in the lesions was related to the clinical symptoms of patients with carotid atherosclerosis." (PMID 35050177, 2022).
cataract (1 paper, 2024). Partial or complete opacity of the crystalline lens of one or both eyes that decreases visual acuity and eventually results in blindness. "The results showed that the Cd74 gene was mainly associated with diseases such as Retinal Diseases, Eye Abnormalities, Cataract, and Vision Disorders." (PMID 38622534, 2024).
cerebral infarction (1 paper, 2022). An ischemic condition of the brain, producing a persistent focal neurological deficit in the area of distribution of the cerebral arteries. "Moreover, in the MIF knockout mice, the expression level of pro-inflammatory markers and CD74+ cells was not affected by the absence of the MIF after cerebral infarction." (PMID 35805977, 2022).
cholangiocarcinoma (1 paper, 2024). A carcinoma that arises from the intrahepatic biliary tree (intrahepatic cholangiocarcinoma) or from the junction, or adjacent to the junction, of the right and left hepatic ducts (hilar cholangiocarcinoma). "In this study, the enhanced interaction between MIF and CD74 + CD44 in cholangiocarcinoma may inhibit tumor apoptosis and promote angiogenesis by activating the downstream PI3K/Akt signaling pathway." (PMID 38702814, 2024).